GOLGA6L5P (golgin A6 family like 5, pseudogene)
Synonyms: FLJ35171; FLJ40113; GOLGA6L8; formerly GOLGA6L5
Gene: Transcribed unprocessed pseudogene on chromosome 15 (84,509,926 to 84,516,785, reverse strand). Ensembl gene ENSG00000230373.
Diseases named in the same sentence as GOLGA6L5P in open-access papers:
GOLGA6L5P is named in the same sentence as 2 diseases in open-access papers, as found by Europe PMC text mining. Sharing a sentence is not in itself a finding about the gene and the disease.
GOLGA6L5P shares sentences with these, for which no sentence is quoted: depression (1 paper); schizophrenia (1).